JTB (jumping translocation breakpoint)
Description:
Required for normal cytokinesis during mitosis. Plays a role in the regulation of cell proliferation. May be a component of the chromosomal passenger complex (CPC), a complex that acts as a key regulator of mitosis. The CPC complex has essential functions at the centromere in ensuring correct chromosome alignment and segregation and is required for chromatin-induced microtubule stabilization and spindle assembly. Increases AURKB activity. Inhibits apoptosis induced by TGFB1 (By similarity). Overexpression induces swelling of mitochondria and reduces mitochondrial membrane potential (By similarity).
Synonyms: HSPC222; hJT; PAR; HJTB
Tractability: Antibody: its Gene Ontology location is reachable by antibodies, with high confidence; UniProt predicts a signal peptide or a membrane-spanning region. PROTAC: ubiquitination databases record sites on it; its protein half-life has been measured.
Gene: Protein-coding gene on chromosome 1 (153,974,269 to 153,977,674, reverse strand). Ensembl gene ENSG00000143543.
Subcellular location: Membrane; Mitochondrion; Cytoplasm; Cytoplasm, cytoskeleton, microtubule organizing center, centrosome; Cytoplasm, cytoskeleton, spindle
Subcellular location (Human Protein Atlas): Mitochondria; Vesicles
Gene Ontology:
Molecular function: protein kinase binding
Biological process: mitotic cell cycle; mitotic cytokinesis; positive regulation of protein kinase activity; regulation of cell population proliferation
Cellular component: centrosome; cytoplasm; midbody; spindle; membrane; plasma membrane; mitochondrion
Genetic constraint (gnomAD): Loss-of-function variants: 10 observed, 20.64 expected, observed/expected ratio (o/e) 0.48, 90% interval 0.3 to 0.82. The upper end of that interval is the gene's LOEUF score, 0.82, which puts it in group 3 of 6, group 1 being the genes least tolerant of losing a copy. Missense variants: 136 observed, 185.97 expected, observed/expected ratio (o/e) 0.73, 90% interval 0.63 to 0.84. Synonymous variants: 81 observed, 69.37 expected, observed/expected ratio (o/e) 1.17, 90% interval 0.98 to 1.4.
Homologues: Orthologues: chimpanzee JTB (100% identical), macaque JTB (94% identical), dog JTB (87% identical), mouse Jtb (84% identical), guinea pig JTB (83% identical), rat Jtb (75% identical), tropical clawed frog jtb (43% identical), zebrafish jtb (27% identical), Drosophila melanogaster JTBR (21% identical), Caenorhabditis elegans jtr-1 (14% identical).
Diseases named in the same sentence as JTB in open-access papers:
JTB is named in the same sentence as 10 diseases in open-access papers, as found by Europe PMC text mining. Sharing a sentence is not in itself a finding about the gene and the disease. The quoted sentences say what the papers report.
breast carcinoma (5 papers, 2022 to 2025). "Overall, JTB emerges as a potential biomarker and therapeutic target in breast cancer, warranting further investigation into its molecular mechanisms and interactions." (PMID 40722776, 2025). "While JTB dysregulation—either overexpression or silencing—has been observed across various cancer types, including breast cancer (BC), prostate cancer (PCa), and MM, its precise role remains ambiguous." (PMID 40722776, 2025). "Hence, JTB could be a tumor biomarker for different types of cancer, such as breast cancer (BC), and could be used as a drug target for therapy." (PMID 36500393, 2022).
prostate carcinoma (3 papers, 2023 to 2025). A carcinoma that arises from epithelial cells of the prostate gland. "JTB is currently investigated as a potential biomarker in several cancer types, including hematologic malignancies, breast cancer and prostate cancer." (PMID 41155247, 2025). "Recent advances in proteomics, alongside genomic and transcriptomic studies, have provided robust evidence for JTB’s role in modulating EMT, metabolism reprogramming, immune evasion, and therapeutic resistance, particularly in breast and prostate cancers." (PMID 40722776, 2025).
hepatocellular carcinoma (2 papers, 2022 to 2023). A malignant tumor that arises from hepatocytes. "Silencing of JTB expression has been cited to promote cancer cell motility and emphasized anti-apoptotic effect in hepatocellular carcinoma (HCC)." (PMID 36500393, 2022). "Thus, JTB was found to be upregulated in many tumor tissues, such as primary BC, compared to normal counterparts, ovary, lung, uterus, colon, rectum, thyroid, prostate, stomach, kidney, and small intestine cancer, as well as in leukemia and hepatocellular carcinoma (HCC)." (PMID 37834160, 2023).
liver cancer (2 papers, 2023). An epithelial or non-epithelial malignant neoplasm that arises from the liver. "JTB protein has been reported as overexpressed in some BC cell lines and primary breast tumors compared with their normal tissue samples counterparts, as well as in prostate and liver cancer." (PMID 37834160, 2023).
ileum cancer (1 paper, 2017). "Other protein-encoding genes (FGL2, CTSB, TPP1, SLCO2B1, NARF and JTB) have disease related functions, such as viral hepatitis and ileum cancer." (PMID 28401895, 2017).
cancer (6 papers, 2020 to 2025). A tumor composed of atypical neoplastic, often pleomorphic cells that invade other tissues. "Furthermore, overexpressed JTB was associated with altered metabolic and stress response pathways, as well as resistance to cancer therapies." (PMID 40722776, 2025). "Of note, TMED2, AGR2, and JTB are known to be associated with poor prognosis in other cancers and thus, could be explored as novel biomarkers for predicting chemo-resistance in PDAC." (PMID 32195182, 2020). "JTB can be explored across genomic, transcriptomic, and proteomic levels, providing a multidimensional understanding of its role in cancer biology and reinforcing its potential as a comprehensive biomarker in translational research." (PMID 40722776, 2025). "In conclusion, the multifaceted nature of JTB in cancer biology, reflected in its genomic context, dynamic expression, molecular interactions, and context-specific functional effects, supports further investigation in clinical research." (PMID 40722776, 2025). "This review synthesizes current knowledge on the genomic, molecular, and proteomic aspects of JTB, its role in cancer biology, and its potential value as a biomarker and therapeutic target." (PMID 40722776, 2025). "By exploring the intricate relationship among JTs, 1q21 amplification, and JTB protein functions, we aim to provide a comprehensive overview of these transcripts and isoproteins within the broader context of cancer genomics and precision medicine." (PMID 40722776, 2025). "While JTB is widely expressed in normal cells, it has been discovered that cancer cells overexpress it61." (PMID 39014082, 2024). "JTB is a gene located on human chromosome 1q21 and is involved in unbalanced translocation in many types of cancer such as lung, stomach and colon and most predominantly in breast and prostate cancer." (PMID 36500393, 2022). "The JTB protein is ubiquitously present in normal cells but is found to be overexpressed in cancer cells." (PMID 36500393, 2022). "These paradoxical findings reinforce the dualistic nature of JTB in cancer biology and highlight its capacity to participate in a wide range of cellular functions, including cell cycle regulation, apoptosis evasion, stress response, immune modulation, and cellular communication with the TME." (PMID 40722776, 2025). "Understanding JTB’s multifaceted contributions to tumor biology may pave the way for novel biomarkers and targeted treatments in cancer management." (PMID 40722776, 2025). "Glyceraldehyde-3-phosphate dehydrogenase 1 (GAPDH1), also upregulated in JTB downregulated condition, is known to play an important role in metabolism and gene transcription; it promotes cancer growth and metastasis by affecting EMT through upregulation of SNAIL expression." (PMID 36500393, 2022). "JTB protein is ubiquitously present in normal cells but it is found to be overexpressed or downregulated in various types of cancer cells, where this protein and its isoforms promote mitochondrial dysfunction, resistance to apoptosis, genomic instability, proliferation, invasion and metastasis." (PMID 36500393, 2022).
tumor (5 papers, 2022 to 2025). "Notably, several downregulated proteins linked to JTB overexpression suggest tumor-suppressive functions, highlighting the context-dependent nature of JTB’s role." (PMID 40722776, 2025). "On the other hand, JTB downregulation promoted similar malignant characteristics, suggesting that both the loss and gain of JTB function can destabilize cellular homeostasis and support tumor progression." (PMID 40722776, 2025). "This review underscores the dual role of JTB as both a tumor suppressor and oncogene, depending on the cellular context, and advocates for its continued investigation at the genomic, transcriptomic, and proteomic levels." (PMID 40722776, 2025). "Collectively, these data support the potential of JTB as a biomarker in BC and underscore the need for further mechanistic studies to elucidate its contribution to tumor initiation and progression." (PMID 40722776, 2025). "Collectively, the findings from molecular, cellular, and proteomics-based studies converge on the conclusion that JTB protein is a complex and context-dependent regulator in BC, with the capacity to function both as an oncogene and a tumor suppressor." (PMID 40722776, 2025). "Nevertheless, the paradoxical and multifaceted impact of JTB dysregulation highlights the necessity for further in vivo and mechanistic studies to determine its precise functional role in tumor initiation and progression." (PMID 40722776, 2025). "Importantly, the use of these different methods uncovered overlapping but also unique sets of proteins and pathways, revealing both pro-tumorigenic and tumor-suppressive roles of JTB, depending on its expression level." (PMID 40722776, 2025). "JTB protein is broadly expressed in normal human tissues; however, its expression is often dysregulated in various malignancies, exhibiting either over- or underexpression, depending on the specific tumor type." (PMID 40722776, 2025). "Intriguingly, proteomics-based studies have revealed that JTB may act as a context-dependent oncogene or tumor suppressor, depending on the cellular environment and regulatory cues." (PMID 40722776, 2025). "Overall, taking into account the opinion of other authors, as well as based on our own team’s in vitro studies, we suggest that JTB protein might be considered as a tumor biomarker for BC and should be studied as a target for BC therapy." (PMID 38005222, 2023). "Interestingly, JTB overexpression has been correlated here with a plethora of significant upregulated and downregulated proteins that sustain JTB tumor suppressive functions." (PMID 37834160, 2023). "Thus, JTB expression detected in the lung, kidney, stomach, and colon decreased significantly in tumor samples compared to normal samples." (PMID 37834160, 2023). "Overall, JTB downregulation drives MCF7 cells toward a phenotype characterized by enhanced proliferation, migration, invasion, and resistance to a hostile tumor microenvironment (TME)." (PMID 40722776, 2025). "Notably, siRNA-mediated silencing of the JTB gene in PC3 cells resulted in a reversion of their malignant phenotype, highlighting a potential role of JTB in driving tumor aggressiveness." (PMID 40722776, 2025). "Silencing JTB in DU145 PCa cells leads to several mitotic defects, including improper chromosome alignment and segregation, failed cytokinesis, increased polyploidy, elevated apoptosis, and mitotic abnormalities that contribute to genomic instability and tumor progression." (PMID 40722776, 2025).
JTB also shares sentences with these, for which no sentence is quoted: breast tumors (1 paper); myeloid malignancies (1); viral hepatitis (1).